ISG20 (interferon stimulated exonuclease gene 20)
Diseases named in the same sentence as ISG20 in open-access papers (continued):
Sharing a sentence is not in itself a finding about the gene and the disease.
ovarian carcinoma (6 papers, 2021 to 2026). A malignant neoplasm originating from the surface ovarian epithelium. "In ovarian cancer, high ISG20 expression was associated with tumor immunogenicity and increased T cells infiltration." (PMID 37342328, 2023). "It was reported that ISG20 overexpression suppressed the proliferation, migration, and invasion in vitro and the growth of xenograft tumors in vivo in ovarian cancer, and it may be associated with a long OS in OV patients." (PMID 36177004, 2022). "Increased IFN-β production was also observed in ovarian cancer cells with elevated ISG20 expression, which was suggested to result from an ISG20-induced accumulation of short dsRNA fragments activating the RIG-I signaling pathway." (PMID 41511982, 2026). "The accumulation of endogenous dsRNA in ovarian cancer cells overexpressing ISG20 is sensed by RIG-I, leading to IFN-β production." (PMID 37342328, 2023). "This study suggests that targeting ISG20 is a potential immune therapeutic approach to treat ovarian cancer." (PMID 37342328, 2023). "Increased infiltration of CD8+ T cells was observed in paraffin-embedded ovarian cancer samples with high ISG20 expression, which was also consistent with TCGA RNA-seq analysis results." (PMID 37342328, 2023). "In this study, we demonstrate that ISG20 plays an important role in activating the IFN signaling pathway in ovarian cancer cells." (PMID 37342328, 2023). "Increased HLA-A expression was also observed in paraffin-embedded ovarian cancer samples with high ISG20 expression." (PMID 37342328, 2023). "First, we used the ESTIMATE tool to infer all immune cells in TCGA ovarian cancer and concluded that the immune score was higher in the ISG20 high subtype." (PMID 37342328, 2023). "To investigate the correlation between ISG20 expression and immune cell infiltration, we compared the composition of the tumor microenvironment between the high and low ISG20 subsets of TCGA ovarian cancer dataset." (PMID 37342328, 2023). "The present study found that ISG20 overexpression resulted in the degradation of endogenous dsRNA into small dsRNA fragments in ovarian cancer cells, thereby triggering IFN-β production via the RIG-I dsRNA sensing pathway." (PMID 37342328, 2023). "This was also reported for ISG20 positive ovarian cancer cells and may involve the enhancement of IFN-beta production and response which is known to be driven by the upregulation of HERVs." (PMID 41511982, 2026). "Here, we found that ISG20 can induce IFN-β production in ovarian cancer cells, suggesting that ISG20 overexpression induction of IFN-β production may depend on cell type, which warrants further investigation." (PMID 37342328, 2023). "Further, elevated ISG20 expression in ovarian cancer cells led to increased IFN-β production." (PMID 37342328, 2023). "Based on our results, we hypothesized that ISG20 can induce type I IFN in ovarian cancer." (PMID 37342328, 2023). "Thus, we also examined CXCL9, CXCL10, CXCL11 in the ovarian cancer cell lines, ES2 and SKOV3, that overexpress ISG20, and found that CXCL10 and CXCL11 were significantly upregulated." (PMID 37342328, 2023). "Therefore, we detected antigen presentation-related genes in the ovarian cancer cell lines, ES2 and SKOV3, which overexpress ISG20." (PMID 37342328, 2023). "To test this hypothesis, we overexpressed ISG20 in SKOV3 and ES2 ovarian cancer cells." (PMID 37342328, 2023).
influenza (5 papers, 2011 to 2025). An acute viral infection of the respiratory tract, occurring in isolated cases, in epidemics, or in pandemics; it is caused by serologically different strains of viruses (influenzaviruses) designated A, B, and C, has a 3-day incubation period, and usually lasts for 3 to 10 days. "Furthermore, this GO analysis indicated that genes associated with the antiviral response to influenza (e.g., Ifi27l2a, Isg20, Oas1a, Isg15, Ifit1, Oasl1, and Ifit3) were strongly enriched in mice vaccinated with WIV alone as compared with mice vaccinated with WT IL-1β or CD8α ALN-1." (PMID 32714571, 2020). "A number of those genes have been shown previously to play a protective role during the influenza infection (e.g. Isg20, Isg15, Gbp1, etc.)." (PMID 24073225, 2013).
glioblastoma (4 papers, 2018 to 2023). The most malignant astrocytic tumor (WHO grade IV). "Differential expression patterns of ISG20 have been shown in the biopsies of various malignancies, including virus-related cancers like glioblastoma and HCC." (PMID 29963243, 2018). "Additionally, ISG20 expression was significantly higher in glioblastoma, followed by astrocytoma, anaplastic oligodendrocytoma, and oligodendroglioma (P < 0.001)." (PMID 37380984, 2023). "High expression of ISG20 is related to poor clinical outcomes in glioblastoma." (PMID 33344083, 2020). "Through analyzing patients’ clinical information and genetic profiles from online databases, TIMP1, ITGA5, FCGR2B, UPP1, ISG20, TSPAN4, and LOXL1 were identified as potential prognostic biomarkers for glioblastoma." (PMID 35778451, 2022). "We found that TIMP1, ITGA5, FCGR2B, UPP1, ISG20, TSPAN4, and LOXL1 are potential biomarkers correlated with the immune infiltration events in patients with glioblastoma." (PMID 35778451, 2022). "In addition, we used the SurvExpress analysis to further assess the prognostic value of TIMP1, ITGA5, FCGR2B, UPP1, ISG20, TSPAN4, and LOXL1 using other glioblastoma patient cohorts, including TCGA Glioblastoma and GSE4412." (PMID 35778451, 2022).
diabetic nephropathy (3 papers, 2021 to 2023). "Long non‐coding RNA (lncRNA) lnc‐ISG20 has been found aberrantly up‐regulated in the glomerular in the patients with diabetic nephropathy (DN)." (PMID 33939247, 2021). "Lnc‐ISG20 controlled NFAT5 expression by sponging miR‐486‐5p in diabetic nephropathy." (PMID 36852438, 2023).
hearing loss (3 papers, 2016 to 2025). "A large-scale ARHL GWAS found that the ISG20 gene locus was significantly associated with hearing loss in elderly people, but its specific mechanism is still unclear." (PMID 41255877, 2025). "This study is the largest GWAS meta-analysis of ARHI to date and identified 7 associated loci, of which 5 are novel (FXYD5, IPP, SPIRE2, SPTBN1 and TRIL) and 2 have been previously related to hearing loss (ILDR1, ISG20)." (PMID 31645637, 2019).
chronic hepatitis B (2 papers, 2017 to 2018). "A recent study has shown that expression levels of the ISG20 protein and ISG20 mRNA were higher in livers of chronic hepatitis B patients responding well to interferon-alpha treatment compared to chronic hepatitis B non-responders." (PMID 29963243, 2018). "Interestingly, chronic hepatitis B patients who had good responses to IFN treatment showed significantly higher levels of ISG20 in their livers compared to either the patients who were non-responders to IFN treatment or the healthy controls." (PMID 28399146, 2017).
chronic viral hepatitis (2 papers, 2018 to 2025). "In line with a constitutive ISG expression in NK cells, we also showed that the expression of IFITM3, IRF1, IFIT2 and ISG20 are refractory to IFN stimulation in vitro in NK cells that were obtained from patients with HD and chronic viral hepatitis." (PMID 40837234, 2025). "Although ISG20 effectively impairs replication of many viruses, particularly that of HAV, HBV and HCV, the relevance of ISG20 serum levels in patients with viral hepatitis and the role of ISG20 in the pathogenesis and clinical outcome of HBV infection has not been established so far." (PMID 29963243, 2018).
Cirrhosis (2 papers, 2006 to 2018). A chronic disorder of the liver in which liver tissue becomes scarred and is partially replaced by regenerative nodules and fibrotic tissue resulting in loss of liver function. "A small set of genes (ISG20, IFI16, TRIM22, STAT5A) were also highly up-regulated in nearly all samples, including ethanol-cirrhotic livers, suggesting these may play a role in an inflammatory response related to cirrhosis development regardless of etiology." (PMID 17121680, 2006).
HCMV infection (2 papers, 2025 to 2026). "Transfection of HFF cells with an ISG20-specific siRNA prior to HCMV infection (strain TB40/E, MOI of 1) resulted in elevated levels of viral early and late proteins, which appeared to be more pronounced when lower virus doses were applied." (PMID 41511982, 2026). "Comparable results were obtained in HFF transfected with ISG20-specific siRNA or control siRNA prior to HCMV infection." (PMID 41511982, 2026). "In summary, the regulation of ISG20 during HCMV infection resembles that of other ISGs with protein levels peaking during the early phase of infection." (PMID 41511982, 2026). "Consistently, we detected that treatment with the JAK-STAT inhibitor ruxolitinib alleviated the inhibitory effect of ISG20 on HCMV infection." (PMID 41511982, 2026). "In summary, we identified several factors that inhibit HCMV infection, with the strongest effect detected for the interferon-stimulated gene ISG20." (PMID 41511982, 2026). "The changes of ISG20 protein levels during HCMV infection also correlated with changes in mRNA levels, as determined through RT-qPCR." (PMID 41511982, 2026). "The only antiviral ISG in our screen that we found to be upregulated in the presence of increased levels of MyD88 and HCMV infection was ISG20." (PMID 40638072, 2025). "While this antiviral activity could not be attributed to the degradation of viral RNA or viral DNA, we observed that ISG20 enhances the expression of other ISGs during HCMV infection." (PMID 41511982, 2026). "Evidence for its contribution to the host cell’s defense against human cytomegalovirus infection is also provided by the observation that ISG20 is transiently upregulated during HCMV infection and counteracted by the interferon-antagonistic immediate-early protein IE1." (PMID 41511982, 2026). "Since the exonuclease ISG20 has been reported to induce the degradation of HBV cccDNA, we wondered whether the inhibition of HCMV infection by ISG20 may be attributed to the degradation of HCMV DNA." (PMID 41511982, 2026). "In order to examine whether ISG20 enhances ISG induction during HCMV infection, HFF/control, HFF/ISG20 and HFF/ISG20mut were infected (HCMV strain AD169, MOI of 1) and harvested at 6 hpi, before ISG expression is blocked by IE1 and other viral proteins." (PMID 41511982, 2026). "To confirm the antiviral function of ISG20 during HCMV infection, we utilized lentiviral vectors to generate HFF cells with doxycycline-inducible overexpression of either wild-type ISG20 (HFF/ISG20) or the catalytically inactive D94G mutant (HFF/ISG20mut), alongside control cells (HFF/control)." (PMID 41511982, 2026). "Since we hypothesize that ISG20 inhibits HCMV replication through inducing antiviral genes such as ISGs, we analyzed HCMV infection in the presence of an inhibitor of IFN signaling, the JAK inhibitor ruxolitinib." (PMID 41511982, 2026).
Hepatitis (2 papers, 2018 to 2024). Inflammation of the liver. "Upregulated ISGs (ISG20, IFI16, TAP2, GBP1, PSMB9) in the hepatitis phase were associated with T cell and macrophage infiltration and positively correlated with ALT levels." (PMID 39135698, 2024). "While many immune genes, including ISG20, have been identified in hepatitis-induced HCC, the biological function of ISG20 in tumorigenesis remains poorly understood." (PMID 29963243, 2018). "Conversely, other ISGs, including ISG20, IFI16, APOBEC3G, CXCL10, and CXCL11, which were predominantly expressed in T cells and nMacs, and upregulated during the hepatitis phase, showed a positive correlation with serum ALT levels, indicating their involvement in liver injury." (PMID 39135698, 2024).
lung carcinoma (2 papers, 2022 to 2024). "The results showed that CD increased ISG20 expression at both the protein and mRNA level in a dose-dependent manner in the H1975 lung cancer-cell line ​ and 22RV1 prostate cancer-cell line ​." (PMID 36177004, 2022).
multiple myeloma (2 papers, 2021 to 2024). "The CERES score of four genes (ISG20, NDC1, SF3B3, UMPS) was significantly lower in the myeloma cell lines (n = 20) compared to in the other cancer cell lines (n = 769)." (PMID 34683129, 2021).
ovarian serous cystadenocarcinoma (2 papers, 2022 to 2024). A malignant serous cystic epithelial neoplasm arising from the ovary. "Interferon-induced anti-viral exoribonuclease (ISG20), acting on single stranded RNA and involved in immune and inflammatory responses, correlated with improved survival in ovarian serous cystadenocarcinoma (OV) and SKCM." (PMID 39662180, 2024).
ZIKV infection (2 papers, 2022 to 2023). "Upon ZIKV infection, the expressions of IFN-related genes (such as IFNL1 and IFNL3) and ISG-related genes (such as ISG15 and ISG20) were only marginally elevated until 24 h.p.i." (PMID 36209057, 2022).
bladder carcinoma (1 paper, 2025). "Our work in the human bladder carcinoma TCCSUP cell line delineates a complex equilibrium between BKPyV and host defenses, where ISG20 serves as both a viral restriction factor and interacts with the viral large T antigen." (PMID 41304224, 2025).
brain tumor (1 paper, 2023). "The fixed effect model of meta-survival analysis showed that ISG20 overexpression was associated with unfavorable prognosis of patients with brain tumor (P < 0.001, HR = 1.17, 95% CI: 1.08–1.27)." (PMID 37380984, 2023). "Using GENT2 which provides reliable prognostic power estimated by the synergetic effect across many independent reports, we first performed a meta-survival analysis of ISG20 in brain tumors with differing histopathological types." (PMID 37380984, 2023).
breast tumor (1 paper, 2021). "We observed that overexpression of ISG20 is increased in metastases compared to matched primary breast tumor tissues." (PMID 34078871, 2021). "We noticed that ISG20 levels were much elevated in primary tumors in comparison to their matched normal tissues, and furthermore ISG20 expression was much higher in LN metastases versus their matched primary breast tumor." (PMID 34078871, 2021).
chronic kidney disease (1 paper, 2021). Impairment of the renal function secondary to chronic kidney damage persisting for three or more months. "Further experimentation in our study revealed that lnc‐ISG20 knockdown could reduce the expression levels of collagen IV, fibronectin and TGF‐β1, among which TGF‐β is the primary factor that drives fibrosis in almost all forms of chronic kidney disease." (PMID 33939247, 2021).
chronic periodontitis (1 paper, 2021). A chronic inflammatory process that affects the tissues that surround and support the teeth. "In chronic periodontitis, researchers detected aberrantly upregulated ISG20 genes in monocytes stimulated by LPS from Porphyromonas gingivalis." (PMID 34285922, 2021).
coinfection (1 paper, 2023). The simultaneous infection of a host by multiple pathogen species. "Furthermore, in LLC-PK cells, the knockdown of ISG20 by siRNA significantly promoted PEDV or PDCoV infection and co-infection of PEDV and PDCoV." (PMID 38257774, 2023). "However, the difference between the ability of ISG20 to inhibit infection with PEDV or PDCoV and that of ISG20 to inhibit PEDV and PDCoV coinfection could not be proven." (PMID 38257774, 2023).
Crohn disease (1 paper, 2024). A gastrointestinal disorder characterized by chronic inflammation involving all layers of the intestinal wall, noncaseating granulomas affecting the intestinal wall and regional lymph nodes, and transmural fibrosis. "However, whether ISG20 is involved in the pathogenesis of Crohn’s disease requires further research." (PMID 38343536, 2024). "In our exploration of the expression of angiogenesis-related genes in Crohn’s disease patients, we found upregulation of OSM, CXCL5, CEACAM3, ISG20, and DUOXA1 genes in Crohn’s disease patients." (PMID 38343536, 2024).
dengue (1 paper, 2012). "Despite the different conditions in vivo, with shifting cell populations and multiple interacting stimuli, 57 of these genes, including canonical ISGs such as ISG15, ISG20, OAS2, ISI27, STAT1 and STAT2, had consistently elevated transcript levels in dengue patients compared to healthy controls." (PMID 23285306, 2012).
herpesvirus infections (1 paper, 2026). "Since ISG20 has hardly been characterized in the context of herpesvirus infections, we wished to further elucidate its role during lytic HCMV replication." (PMID 41511982, 2026).
HIV-1 infection (1 paper, 2019). The type species of lentivirus and the etiologic agent of acquired immunodeficiency syndrome (AIDS). "In addition, significant changes were observed in the expression of coding genes involved in the host response to infection (e.g., ISG15, STAT1, OAS3, ISG20, CCL2, and MX1), confirming robust HIV-1 infection of these cells." (PMID 31551335, 2019).
injury (1 paper, 2015). Damage inflicted on the body as the direct or indirect result of an external force, with or without disruption of structural continuity. "The up-regulation of Isg20 has been found after different kinds of brain injury." (PMID 26556046, 2015).
kidney injury (1 paper, 2023). Trauma to the kidney. "Expression of ISGs (Mx1, Isg15, Isg20, Ifitm1, Bst2, and Oas1), and immune cell markers Lyz2 and Cd68 were markedly lower in 3TC mice with FA-induced kidney injury compared to controls." (PMID 36732547, 2023).
liver diseases (1 paper, 2018). "In the patient group, varying ISG20 levels were associated with different forms of HBV-related liver diseases." (PMID 29963243, 2018). "This study investigates ISG20 serum levels in Vietnamese patients with HBV-related liver diseases and their association with clinical progression of HBV infection." (PMID 29963243, 2018). "We have shown that ISG20 levels are significantly modulated in patients with HBV-related liver diseases, especially in patients with HCC." (PMID 29963243, 2018). "The results of the comparisons show that ISG20 levels were significantly elevated in patients with HBV-related liver diseases compared to the controls (19.3 ng/ml vs. 10.9 ng/ml, P<0.0001), indicating that ISG20 levels are modulated due to HBV infection." (PMID 29963243, 2018). "In conclusions, ISG20 levels are induced by HBV infection and significantly associated with progression and clinical outcome of HBV-related liver diseases, especially in patients with HCC." (PMID 29963243, 2018). "In conclusion, ISG20 levels are modulated during the progression of HBV infection and significantly associated with the clinical outcome of HBV-related liver diseases, especially in patients with HBV-related HCC." (PMID 29963243, 2018). "The present study has determined the serum levels of ISG20 in different forms of HBV-related liver diseases as well as in healthy individuals." (PMID 29963243, 2018). "The positive correlation observed in HBV patients may be due to the fact that the age of patients is higher in groups with advanced liver diseases and that the presence of advanced liver diseases certainly affects expression and production of ISG20." (PMID 29963243, 2018). "However, further studies are required to examine the functional role and prognostic potential of ISG20 in HBV-related liver diseases, especially in tumorigenesis." (PMID 29963243, 2018). "ISG20 levels were measured in patients with HBV-related liver diseases and in controls." (PMID 29963243, 2018). "Although our results show a potential role of ISG20 in HBV infection, the mechanisms by which ISG20 triggers HCC development and affects the clinical outcomes of HBV-related liver diseases need to be further elucidated." (PMID 29963243, 2018).
lupus nephritis (1 paper, 2025). Glomerulonephritis in the context of systemic lupus erythematosus. "Previously, ISG20 has been reported to act as a mediator of CX3CL1 production, thereby inducing glomerular inflammation, particularly in patients with lupus nephritis." (PMID 40622935, 2025).